TNF (tumor necrosis factor)
Diseases named in the same sentence as TNF in open-access papers (continued):
Sharing a sentence is not in itself a finding about the gene and the disease.
cervical carcinoma (continued). "In this study, we demonstrated that dihydrocapsaicin (DHC), a major capsaicinoid found in red peppers, enhances tumor necrosis factor-α (TNF-α)-induced G1 cell cycle arrest and apoptosis in HeLa human cervical cancer cells through the suppression of TAK1-mediated NF-κB and EGFR survival pathways." (PMID 40507823, 2025). "EGFR, TNF-α, and VEGFA are the key targets related to the prognosis of cervical cancer." (PMID 40238841, 2025). "As a result, both PRME extract and puerarin showed a pattern of reducing various proinflammatory cytokine levels, including IL-2, IL-12, IFN-γ, and TNF-α, in HeLa cells, thereby proving that the PRME extract and puerarin also have anti-inflammatory effects in human cervical cancer cells." (PMID 39941110, 2025). "However, the role of NMB in cervical cancers is limited to tumor proliferation via ERK1/2 and NF-κB pathways and TNF-α upregulation." (PMID 39214988, 2024). "CaSki cervical cancer cells were exposed to TNF-α and TGF-β1 and treated or not with PTX for 5 days, and a wound-healing assay was determined to examine the effect of PTX on cell migration by taking photographs at 0, 6, 12, and 24 h after wound generation." (PMID 37445768, 2023). "In hrHPV-induced cervical cancer and HNSCC, expression of immunostimulatory T helper 1 (Th1) cytokines such as interleukin 2 (IL-2), IL-12, tumor necrosis factor α (TNF-α), and IFNs is downregulated, whilst Th2 proinflammatory and immunosuppressive cytokines are overexpressed." (PMID 37112681, 2023). "Therefore, we identified 52 PRGs from the TCGA database and screened three Differentially Expressed Pyroptosis-Related Genes (DEPRGs) in the prognosis of cervical cancer: CHMP4C, GZMB, TNF." (PMID 35574296, 2022). "This study aims to investigate the clinical efficacy of chemotherapy combined with traditional Chinese medicine in patients with cervical cancer and its effect on cellular immunoglobulin, serum sugar chain antigen 125 (CA125), carcinoembryonic antigen (CEA), and tumor necrosis factor-α (TNF-α)." (PMID 35035510, 2022). "Cucurbitacin B was shown to down-regulate the TNF-α-induced expression of NF-κB target genes and inhibit the transactivation activity of RelA without suppressing its nuclear translocation in human cervical carcinoma HeLa cells." (PMID 35806134, 2022). "In contrast to these findings, another study demonstrated that cucurbitacin B did not affect TNF-α-induced nuclear RelA translocation but inhibited its transcriptional activity in human cervical carcinoma HeLa cells." (PMID 35806134, 2022). "The most activated signalling pathway of stage II tumour macrophages is the TNF-α pathway, this accords with a recent study showing the serum level of TNF-α expression in patients with cervical cancer was noticeably elevated, which gradually became normal after the surgical treatment." (PMID 36497272, 2022). "Therefore, this study explores the clinical effects of Chinese herbal decoction combined with basic chemoradiotherapy and nursing intervention on cervical cancer and the effects on CEA, CA125, and TNF-α levels." (PMID 34603461, 2021). "In addition, we found that ICA inhibited cervical cancer SiHa cells proliferation, migration, invasion, and the expression levels of TGF-β1, TNF-α, IL-6, IL-17A, and IL-10, as well as promoted cell apoptosis." (PMID 33849528, 2021). "However, recent research has demonstrated that blocking HO-1 in various cervical cancer cell lines augmented the expression of INF-γ and TNF-α in the co-cultured NK cells and restored the expression of NK cell markers, namely: NKG2D, NKp30 and NKp46." (PMID 33287312, 2020). "Moreover, TNF-α expression was correlated with insufficient modulation of IFN-γ and inversely correlated with HPV16 E6 and E7 transcripts in cervical cancer cases." (PMID 30847024, 2019). "We next determined the combined effect of TNF and TRAIL on cervical cancer-derived cells." (PMID 30625987, 2019).
cervical carcinoma (continued). "TNF also interacts physically with the TNF receptor TRAF2, as shown in a cervical cancer cell line." (PMID 31681304, 2019). "In particular, a negative feedback regulation of NF-κB/miR-130a/TNF-α/NF-κB has been described in cervical cancer cells." (PMID 30374356, 2018). "To see the impact of TNF‐α on the apoptosis of cervical cancer cell, we incubated the tumour cell with various concentration of TNF‐α but no notable alteration in the apoptosis rate was seen between TNF‐α‐ and vehicle‐treated cell." (PMID 29632814, 2018). "Matsumiya and colleagues demonstrated that TNFα at a concentration of 10 ng/ml or higher induces IFNε mRNA expression by near twofold in HeLa cells, a cervical cancer cell line, although TNFα did not induce the IFNε promoter activity in this study." (PMID 29118969, 2017). "Altogether, TNF-α initially stimulated NF-κB activation to induce miR-130a expression, which in turn targeted and down-regulated TNF-α expression and suggests a TNF-α/NF-κB negative feedback loop acting through miR-130a in cervical cancer cells." (PMID 24885472, 2014). "Furthermore, low TNF-α concentrations stimulated NF-κB activity and then induced miR-130a expression, and TNF-α overexpression rescued the effects of miR-130a on cervical cancer cells." (PMID 24885472, 2014). "Cervical cancer is mainly initiated by HPV infection, and TNF-α is an inflammatory cytokine which may play important roles in the progression of cervical lesions." (PMID 24015171, 2013). "It has been well accepted that cervical cancer is mainly initiated by HPV infection, and tumor necrosis factor-alpha (TNF-α) is an inflammatory cytokine which may play important roles in the immune response of cervical lesions." (PMID 24015171, 2013). "Luteolin, a plant flavonoid, greatly sensitized TNF-α induced apoptotic cell death in a number of human cancer cell lines including cervical cancer cells by inhibiting TNF-α induced activation of nuclear transcription factor-kappa B, the main survival factor in TNF-α signaling." (PMID 23675041, 2007). "This negative feedback regulation of NF-κB/miR-130a/TNF-α/NF-κB may provide insight into the carcinogenesis of cervical cancer." (PMID 29225578, 2017). "Findings from qPCR analysis were further validated by a microarray analysis (data not shown), which indicated substantial TNF up-regulation (relative expression ratio 3.08) as well as notable upregulation of DR5 (relative expression ratio 7.46) in cervical cancer cells following exposure to Cu E." (PMID 28487767, 2017). "However, Gostout BS found that TNF-α-308G > A does not increase the incidence rate of cervical cancer (OR (95% CI) =0.98 [0.64, 1.50])." (PMID 25928231, 2015). "Moreover, ectopic TNF-α expression lacking the 3’UTR abrogated the effects of miR-130a on cervical cancer cell growth in the colony formation assay, but cell viability assessed by MTT assay was not obviously affected." (PMID 24885472, 2014). "Indeed, it is currently thought that the activities of TNF-α and TGF-β1 arise as a result of the synergistic action of the NF-κB/TGF-β pathways; these findings provide evidence that NF-κB and TGF-β signaling enhances the EMT and the invasiveness of cervical cancer cells." (PMID 37445768, 2023).
cervical carcinoma (continued). "Hence, we shed light on the negative feedback regulation of NF-κB/miR-130a/TNF-α/NF-κB in cervical cancer and may provide insight into the carcinogenesis of cervical cancer." (PMID 24885472, 2014). "However, the expression level of TNFRI and TNFRII in the tumor cells of cervix carcinoma may not be sufficient for allowing cytolytic changes induced by TNF-α." (PMID 18257926, 2008). "HeLa cervix carcinoma cells do not express 5-LO and readily upregulate PGE2 formation upon treatment with TNFα and IL-1β (T/IL) within hours." (PMID 35126121, 2021). "To confirm that miR-130a promotes cervical carcinoma cell growth through at least a partial downregulation of TNF-α, we generated a TNF-α expression vector (pcDNA3/TNF-α) lacking the TNF-α 3’UTR to minimize miRNA interference." (PMID 24885472, 2014). "In cervical cancer cells, upregulated miR-130a directly targeted the 3′ UTR of TNF-α and reduced its expression, and then downregulated TNF-α-activated NF-κB activity and enhanced miR-130a expression by a negative feedback loop of NF-κB/miR-130a/TNF-α/NF-κB." (PMID 29616037, 2018).
hepatitis B (170 papers, 2008 to 2026). "Next, KEGG analysis demonstrated that the DEGs were enriched in biological pathways, such as hepatitis B, pathogenic Escherichia coli infection, and tumor necrosis factor (TNF) signaling pathway." (PMID 39743646, 2025). "This was evident in the IL-17, the Toxoplasmosis, the AGE-RAGE signaling pathway, Hepatitis B, and TNF signaling pathways, which were enriched in SC-associated hub gene targets closely related to UC." (PMID 37078344, 2024). "As only 1/2,500 patients in low prevalence countries treated with TNFα inhibitors develop TB or viral hepatitis B, we suggest an individualized, risk-based approach, rather than universal screening for all patients." (PMID 36744250, 2023). "KEGG pathway analysis suggested that the NOD‐like receptor signaling pathway, Hepatitis B, pathogenic Escherichia coli infection, Salmonella infection, and the TNF signaling pathway were all involved in the DEGs, among others." (PMID 35651286, 2023). "This type of link between HLA and TNF polymorphism has been described for chronic disease development, instead of spontaneous resolution, after hepatitis B infection." (PMID 35769584, 2022). "It is worth mentioning that TNFα:rs1800629 was strongly associated with the resolution of hepatitis B virus (HBV) infection and reported in susceptibility to human papillomavirus (HPV) infection." (PMID 31817071, 2019). "Higher doses of the TNF-α inhibitor were also associated with increased risks of hepatitis B and TB reactivation among patients in this study." (PMID 30373275, 2018). "A higher accumulated dosage of anti-TNF-α agents was associated with increased risks of hospitalization (HR = 3.3), operation (HR = 2.9), hepatitis B (HR = 4.3), and TB (HR = 5.1) reactivation." (PMID 30373275, 2018). "Thiopurine, anti-TNF-α antibody, and steroids were all associated with increased risks of TB and hepatitis B reactivation, which are critical safety concerns in Asia." (PMID 30373275, 2018). "Treatments with thiopurine, corticosteroids, and anti-TNF-α agents were correlated with increases in the associated risks of infection-related hospitalization as well as hepatitis B and TB reactivation." (PMID 30373275, 2018). "The risk of reactivation of diseases such as hepatitis B by these anti-TNFα antibody therapies, has led to recommendations of additional screening before commencing therapy." (PMID 21798078, 2011). "It is known that anti-TNF therapies may affect hepatitis B, causing the reactivation and/or acceleration of preexisting liver damage." (PMID 37111283, 2023). "According to the KEGG analysis results, pathways in cancer, viral carcinogenesis, TNF signaling pathway, Salmonella infection, pathogenic Escherichia coli infection, IL−17 signaling pathway, hepatitis B, chemical carcinogenesis-receptor activation, and apoptosis were significantly enriched." (PMID 36936916, 2023). "Conclusions: 5-ASA usage is associated with decreased risks of hospitalization and operation for patients with IBD, whereas thiopurine, corticosteroids, and anti-TNF-α agents are associated with increased risks of hospitalization and hepatitis B and TB reactivation." (PMID 30373275, 2018). "However, Lu reported that the -238G/A polymorphism of TNF-α associated with the outcomes of hepatitis B virus infection." (PMID 18312678, 2008). "Hepatitis B virus infection induces inflammatory cytokine secretion (e.g., TNF-α, IL-1β, IL-6), which promotes bone resorption and reduces bone formation by activating osteoclasts and inhibiting osteoblast function." (PMID 41404370, 2025). "The signaling pathways regulated by PZH, included those involved in cancer, glucose metabolism, hepatitis B, TNF, and IL-17." (PMID 41181146, 2025). "Through KEGG analysis, it was revealed that TR’s anti-AP pathway primarily encompasses signaling pathways such as IL-17, TNF, Hepatitis B, and PI3K-Akt signaling pathway, among others." (PMID 39568590, 2024).
hepatitis B (continued). "The screening rates and awareness of physicians providing anti-tumor necrosis factor-alpha therapy for hepatitis B virus infection were found to be higher compared to similar studies." (PMID 39045935, 2024). "The immune simulation results of the classical hepatitis B vaccine closely aligned with the responses observed in real vaccine immunizations, such as significant increases in IL-2- and TNF-α-producing cells, particularly CD8+ T cells." (PMID 39703502, 2024). "These pathways encompass AGE-RAGE, IL-17, TNF, Hepatitis B, NF-κB, Influenza A, and PI3K–Akt signaling pathways, with the majority being intricately associated with inflammation." (PMID 39568590, 2024). "Guidelines recommend that patients who will be given anti-TNF-α therapy should be screened for hepatitis B. HBsAg, anti-HBc, and anti-HBs should be checked in these patients." (PMID 39045935, 2024). "Based on the results of the KEGG pathway analysis, most genes were enriched in TNF signaling pathway, hepatitis B, small cell lung cancer, measles, and human immunodeficiency virus 1 infection." (PMID 39466748, 2024). "The core of subnetwork 2 is ESR1, CASP3, and IL6, which are closely related to the TNF signalling pathway and the hepatitis B pathway." (PMID 36818231, 2023). "In the Division of Gastroenterology only 30% of patients with IBD starting anti-TNF medications had evidence of hepatitis B immunity." (PMID 36937959, 2023). "In the gastroenterology clinic, only 30% of patients with IBD starting anti-TNF medications had evidence of hepatitis B immunity." (PMID 36937959, 2023). "Overall, 1% of patients developed TB or viral hepatitis B. TB cases/1,000 TNFα-inhibitor patients were 4-fold higher in Asia, Africa, and South America than in Europe, North America, and Australasia where only 0%-0.4% of patients developed TB." (PMID 36744250, 2023). "The pathway enrichment results suggested that the key targets were mostly involved in pathways in cancer, hepatitis B, TNF signaling pathway, and MAPK signaling pathway." (PMID 35330838, 2022). "In our study, GO and KEGG pathway enrichment analysis of DEOSGs in HCC patients also indicated that DEOSGs were mainly involved in MAPK/TNF signaling pathway, chemical carcinogenesis, hepatitis B and nonalcoholic fatty liver disease." (PMID 36277962, 2022). "In the KEGG enrichment analysis, 165 pathways were identified, including the lipid and atherosclerotic pathway, IL-17 signaling pathway, TNF signaling pathway, hepatitis B pathway, and the AGE–RAGE signaling pathway in diabetic complications." (PMID 36558908, 2022). "The top five pathways include hepatitis B, pathways in cancer, TNF signaling pathway, toxoplasmosis, and toll-like receptor signaling pathway." (PMID 36212968, 2022). "In the serum of hepatitis B patients, cytokines such as TNF-α and interferon γ can upregulate transcription factor C/EBPβ, which then elevate the expression of S100A8/A955,56." (PMID 34645932, 2022). "Other top KEGG enrichment pathways include hepatitis B, the TNF signaling pathway, toxoplasmosis, and the toll-like receptor signaling pathway." (PMID 36212968, 2022). "Through cluster analysis of the 35 KEGG results, eight categories were obtained, of which those with a count of more than 10 were hepatitis B, American trypanosomiasis, TNF signaling pathway, influenza A, and Amoeba protozooses." (PMID 35371275, 2022). "In the KEGG signaling pathway group, the selected genes were related to the interaction between cytokines and their receptors, HIF-1 and TNF signaling pathways, hepatitis B, apoptosis, and cancer-related pathways." (PMID 33849578, 2021). "Three PPI clusters were identified and enriched in hepatitis B and tumor necrosis factor (TNF) signaling pathway, apoptosis and hepatitis B pathway, and peroxisome pathway, respectively." (PMID 33747110, 2021).